NR2F2 (nuclear receptor subfamily 2 group F member 2)
Diseases named in the same sentence as NR2F2 in open-access papers (continued):
Sharing a sentence is not in itself a finding about the gene and the disease.
hypospadias (3 papers, 2022 to 2025). Hypospadias is the displacement of the urethral meatus on the ventrum of the penis. "More recently, rare variants in NR2F2 have been associated with cryptorchidism, hypospadias, and defective penile growth in human patients." (PMID 40637239, 2025). "More recently, defects in the external genitalia (micropenis, hypospadias) and cryptorchidism have been associated with rare heterozygous variants in NR2F2 in 46,XY patients." (PMID 40637239, 2025). "Here, we identified a novel de novo, likely disease causing (REVEL 0.992) variant within the ligand-binding domain of the NR2F2 gene (p.R246H) in a 46, XY boy with micropenis and hypospadias." (PMID 36110220, 2022). "Embryonic deletion of Nr2f2 in mouse testes results in differences of sex development, including dysgenic testes, Leydig cell hypoplasia, cryptorchidism, and hypospadias." (PMID 40295478, 2025). "Embryonic deletion of Nr2f2 in mouse testes led to phenotypes of DSDs, including dysgenic testicles, fetal Leydig cell hypoplasia, cryptorchidism, and hypospadias." (PMID 40295478, 2025). "In summary, embryonic deletion of Nr2f2 in mouse testes resulted in dysgenic testicles, fetal Leydig cell hypoplasia, cryptorchidism and hypospadias, which are typical features of DSDs." (PMID 40295478, 2025). "Our Nr2f2 knockout mouse model recapitulated most of the human phenotypes, including dysgenic testes, reduced testicular interstitium, Leydig cell hypoplasia, cryptorchidism and hypospadias." (PMID 40295478, 2025). "We identified a novel de novo NR2F2 missense variant of uncertain significance (p.R246H) carried by a 46, XY boy (DSD 37), who presented with micropenis and hypospadias and no other somatic anomalies." (PMID 36110220, 2022). "The Nr2f2 cKO testes were not able to produce sufficient testosterone and INSL3 to facilitate proper genital differentiation and testicular descent, resulting in hypospadias and cryptorchidism." (PMID 40295478, 2025).
lung carcinoma (3 papers, 2011 to 2024). "This highlights the novelty of the present study, which suggests that blockade of Wnt/NR2F2/GPX4 axis may serve as a novel therapeutic strategy for improving the effect of chemotherapy in lung cancer BM." (PMID 34586745, 2021). "However, this is the first study to investigate whether the transcriptional regulation of GPX4 is via the Wnt/NR2F2 axis or its promoting role in the acquisition of chemoresistance by lung cancer BM." (PMID 34586745, 2021). "In primary lung cancer, NR2F1 and NR2F2 influence the migration and invasion of tumor cells, while NR2F6 acts as an immune checkpoint factor to modulate immune processes." (PMID 39311119, 2024). "The generation of specific lung cancer animal models for NR2F1, NR2F2, and NR2F6 will not only enhance the understanding of the molecular mechanisms of lung cancer but also improve the diagnosis and therapy for lung cancer associated with NR2F family dysregulation." (PMID 39311119, 2024). "Furthermore, NR2F2 is regulated by the Wnt signaling pathway to activate the expression of GPX4, which could induce high glutathione (GSH) consumption to inhibit ferroptosis and lead to the drug resistance of lung cancer cells that metastasize to the brain." (PMID 39311119, 2024).
Type 2 diabetes (3 papers, 2012 to 2022). "It has been described that hyperinsulinemia, observed during Type 2 diabetes, can activate NR2F2 which can induce development of different diseases." (PMID 36451736, 2022).
breast neoplasm (2 papers, 2012 to 2021). A benign or malignant neoplasm of the breast parenchyma. "NR2F2 is involved in the progression of prostate adenocarcinoma, and NR2F2 expression is a prognostic factor for breast neoplasms." (PMID 33541291, 2021).
cardiac hypertrophy (2 papers, 2018 to 2022). "Moreover, Nr2f2 overexpression had no impact on cardiac hypertrophy but exacerbated fibrosis in DIHF mice and the fibrosis area of the AAV9-cTNT-Nr2f2-Con group was larger than that of AAV9-cTNT-ctrl-Con group (fibrosis area: 25.17 ± 2.843 vs. 19.37 ± 1.590)." (PMID 36081650, 2022).
cryptorchidism (2 papers, 2025). The failure of one or both testes of a male fetus to descend from the abdomen into the scrotum during the late part of pregnancy. "We conclude that defective FLC development in Nr2f2 mutants results in cryptorchidism and impaired masculinization of the external genitalia." (PMID 40637239, 2025).
diaphragmatic hernia (2 papers, 2021 to 2022). A congenital or acquired weakness or opening in the diaphragm which allows abdominal contents to protrude into the chest cavity; congenital diaphragmatic hernias are caused when the embryonic diaphragm fails to fuse. "Consistent with this, Nr2f2-knockout mice develop diaphragmatic hernia." (PMID 35892611, 2022). "Concurrently, knockout mice for NR2F2 (formerly called COUP-TFII) and ZFPM2 (also known as FOG2), both modulators of RA transcriptional activity, exhibit diaphragmatic hernia and lung hypoplasia." (PMID 34831210, 2021).
glioma (2 papers, 2021 to 2023). A benign or malignant brain and spinal cord tumor that arises from glial cells (astrocytes, oligodendrocytes, ependymal cells). "The results showed that STAT1, CREM, and NR2F2 were the most likely upstream TFs of SERPINF1 in glioma." (PMID 36980858, 2023). "In glioma, NR2F2 hypermethylation is a differentially expressed methylated gene between glioma patients with better prognosis and poor prognosis, which is enriched in diseases and disorders in both molecular and cellular aspects." (PMID 34796198, 2021). "Furthermore, STAT1, CREM, and NR2F2 may participate in the transcriptional regulation of SERPINF1 in glioma." (PMID 36980858, 2023). "The top five TFs with the highest correlations in both datasets consisted of STAT1, MEOX2, CREM, NR2F2, and IRF3, indicating that they were likely to regulate the expression of SERPINF1 in glioma." (PMID 36980858, 2023).
male infertility (2 papers, 2008 to 2012). The inability of the male to effect fertilization of an ovum after a specified period of unprotected intercourse. "The NR2F2 locus (15q26.2) encodes a nuclear receptor important in testicular Leydig cell function, the primary source of gonadal testosterone production, and has been linked to male infertility." (PMID 22829776, 2012).
prostate adenocarcinoma (2 papers, 2021 to 2025). "COUP-TFII (NR2F2) promotes prostate tumorigenesis by inhibiting TGF-β-induced growth barriers and correlates with increased lymphangiogenesis and lymph node metastasis in prostate adenocarcinoma." (PMID 39364872, 2025).
Tetralogy of Fallot (2 papers, 2016 to 2023). A congenital cardiac malformation comprising pulmonary stenosis, overriding aorta, ventricular septum defect, and right ventricular hypertrophy. "The nuclear receptor subfamily 2, group F, member 2, Nr2f2, has been associated with congenital heart defects and tetralogy of Fallot in humans." (PMID 26979619, 2016). "Pathogenic mutations in the NR2F2 and GPC3 will lead to many cardiac defects, such as VSD, Tetralogy of Fallot and double outlet right ventricle." (PMID 36874970, 2023).
adenoma (1 paper, 2009). A neoplasm arising from the epithelium. "Except for NR2F2 (p<0.954), all genes were differentially expressed not only between the three subclasses of adenomas (t-test, p<0.05), but also between the four groups of follicular tumors (F-tests, p<0.05 for ADAMTS2, CABIN1, ALDH13, USP13; p = 0.06 for KRTHB5)." (PMID 19893615, 2009).
Anxiety (1 paper, 2023). Intense feelings of nervousness, tension, or panic often arise in response to interpersonal stresses. "In the mature hippocampus, the expression of Nr2f1 is higher in the dorsal hippocampus, which is related to spatial learning and memory, and the expression of Nr2f2 is mainly in the ventral hippocampus, which is associated with emotion and anxiety (a)." (PMID 37751231, 2023).
Arrhythmia (1 paper, 2023). Any cardiac rhythm other than the normal sinus rhythm. "While it is presently unclear if there are also accompanying arrhythmias or conduction defects in these patients, given our results, we speculate that further evaluation of patients with NR2F2 mutations will show that they have or are at higher risk to develop arrhythmias." (PMID 37184369, 2023).
atrial septal defect (1 paper, 2023). Interauricular communication is a congenital malformation characterized by a communication between the atrial chambers of the heart. "Similar to NKX2.5, NR2F2 mutations in humans have now been associated with myriad CHDs, including atrial septal defects and AVSDs." (PMID 37184369, 2023).
Bicuspid aortic valve (1 paper, 2025). The presence of an aortic valve with two instead of the normal three cusps (flaps). "NR2F2 variants/mutations that affect the cooperation of NR2F2 with GATA4 have also been associated with congenital bicuspid aortic valve." (PMID 41153848, 2025).
cardiac abnormalities (1 paper, 2023). "While NR2F2 mutations mainly cause congenital cardiac abnormalities (OMIM 615779), developmental delay is also seen in some patients." (PMID 36579832, 2023).
craniosynostosis (1 paper, 2021). Craniosynostosis is defined as the premature fusion of one or more cranial sutures leading to secondary distortion of skull shape resulting in skull deformities with a variable presentation. "NR2F2 also regulates Runx2, which has been reported to be overexpressed in some types of craniosynostosis, and has a function in the retinoic acid signaling pathway regulation, which is key in the development of CDH." (PMID 34900871, 2021).
erectile dysfunction (1 paper, 2025). Persistent or recurrent inability to achieve or to maintain an erection during sexual activity. "While Hattori and Fukami identified that variants of NR2F2 are associated with testicular sex development and testosterone secretion, the impact of this gene on erectile dysfunction has not been extensively studied." (PMID 40943369, 2025).
esophageal adenocarcinoma (1 paper, 2021). A malignant tumor with glandular differentiation arising predominantly from Barrett mucosa in the lower third of the esophagus. "High expression of NR2F2 in certain gastric and esophageal adenocarcinomas is associated with abnormal expression of cadherin 11, suggesting that the NR2F2-related embryonic pathways in these tumors are reactivated." (PMID 33541291, 2021).
Fanconi anaemia (1 paper, 2020). "Recently it has been shown that FANCD2 can form a complex with NR2F2 or NR2C2, independently from the Fanconi anaemia (FA) core complex or monoubiquitination of FANCD2." (PMID 33244044, 2020).
Hyperglycemia (1 paper, 2025). An increased concentration of glucose in the blood. "We discovered that the NR2F2–MTERF3–GDF15 axis is involved in hyperglycemia-induced repression of oxidative metabolism in the skin, suggesting potential roles for MTERF3 and GDF15 in glucose homeostasis and dermal resilience." (PMID 40174478, 2025). "•NR2F2 activates MTERF3 and inhibits GDF15 upon hyperglycemia." (PMID 40174478, 2025). "Thus, our data reveal a concerted repression of mitochondrial function in the human dermis driven by the interplay among NR2F2, MTERF3, and GDF15, offering a new perspective on hyperglycemia-induced tissue alterations." (PMID 40174478, 2025). "Understanding the interplay of NR2F2, MTERF3, and GDF15 broadens our grasp of hyperglycemia's tissue-specific impacts and may inform future therapeutic strategies targeting mitochondrial health." (PMID 40174478, 2025).
insomnia (1 paper, 2025). A sleep disorder characterized by difficulty in falling asleep and/or remaining asleep. "NR2F2 was associated with both daytime sleepiness and insomnia." (PMID 39880903, 2025).
Insulin resistance (1 paper, 2012). Increased resistance towards insulin, that is, diminished effectiveness of insulin in reducing blood glucose levels. "In conclusion, our data suggest that NR2F2 might be a key factor in novel strategies aiming to prevent or treat some of the metabolic defects related to insulin resistance in humans." (PMID 22606236, 2012).
Leydig cell tumor (1 paper, 2025). A sex cord-stromal tumor occurring in the testis and rarely in the ovary. "Interestingly, while Nr2f2 is not expressed in non-proliferative mouse fetal Leydig cells, Nr2f2 is expressed in proliferative mouse Leydig cell tumor cell lines, such as MA-10 and MLTC-1, where it cooperates with Nr5a1 to drive the expression of steroidogenic genes." (PMID 40295478, 2025).
liver cancer (1 paper, 2022). An epithelial or non-epithelial malignant neoplasm that arises from the liver.
mesothelioma (1 paper, 2023). A usually malignant and aggressive neoplasm of the mesothelium which is often associated with exposure to asbestos. "With this system, we confirmed that knockdown at the TSS of NDC1 and AAAS, two components of the nuclear pore complex, or silencing a putative enhancer of the nuclear receptor NR2F2, decreased the proliferation of mesothelioma cell lines but not of uveal melanoma." (PMID 37400441, 2023).
metabolic syndrome (1 paper, 2012). A cluster of metabolic risk factors for CARDIOVASCULAR DISEASES and TYPE 2 DIABETES MELLITUS. "The role of NR2F2 regulation in the aetiology of complex metabolic diseases, such as the metabolic syndrome and T2D has yet to be fully understood." (PMID 22606236, 2012).
metastatic melanoma (1 paper, 2023). A melanoma that has spread from its primary site to another anatomic site. "To functionally test the contribution of NR2F2-Iso2 to metastatic melanoma progression we performed loss-of-function (LOF) and gain-of-function (GOF) experiments." (PMID 37015919, 2023). "Our study unearthed a mechanism by which epigenetic changes in DNA methylation inhibit NR2F2-Iso2 expression in melanocytes and enable its re-expression in human metastatic melanoma." (PMID 37015919, 2023). "Although our studies do not support a general turnaround of the melanocyte-to-NCC CpG-methylation profile during metastatic melanoma progression, they suggest metastatic progression depends on the reversal of NR2F2-Iso2 repression." (PMID 37015919, 2023). "Collectively, our data suggest that NR2F2-Iso2 becomes epigenetically repressed when NCCs differentiate into melanocytes and it becomes aberrantly re-expressed during metastatic melanoma progression." (PMID 37015919, 2023). "Conversely, this process is reversed during metastatic melanoma progression, when NR2F2-Iso2 becomes increasingly hypomethylated and re-expressed." (PMID 37015919, 2023). "We further found that NR2F2-Iso2 methylation correlates inversely with NR2F2-Iso2 expression, being detected in NCCs but not in melanocytes and increasingly expressed from primary to metastatic melanoma tissues." (PMID 37015919, 2023). "Conversely, NR2F2-Iso2 was increasingly hypomethylated from primary to metastatic melanoma." (PMID 37015919, 2023). "The ratio of NR2F2-Iso2/ NR2F2-Iso1 expression goes up from primary to metastatic melanoma." (PMID 37015919, 2023). "However, we already found NR2F2-Iso2 enhances the expression of EMT and angiogenesis regulatory gene sets in human metastatic melanoma." (PMID 37015919, 2023).
oral cancer (1 paper, 2021). "In oral cancer, it has been found that NR2F2 is hypermethylated in cancer tissue compared to normal tissue, which may play a critical role in oral cancer." (PMID 34796198, 2021).
osteosarcoma (1 paper, 2022). A usually aggressive malignant bone-forming mesenchymal neoplasm, predominantly affecting adolescents and young adults. "Based on our analysis, we found that several NRs including NR4A2, NR4A1, NR3C1, NR2F6, and NR2F2 were differentially expressed in osteoblastic cells among metastasis, primary, and recurrent osteosarcomas." (PMID 35965537, 2022). "In “Pericyte”, differentially expressed NRs such as NR4A1, NR3C1, NR2F2, NR2F1, NR1H2, and ROR were detected among metastasis, primary, and recurrent osteosarcoma tissues." (PMID 35965537, 2022).
Papillary Thyroid Cancer (1 paper, 2026). "This suggests that the NR2F2-BGN axis plays a pivotal role in the pathogenesis of Papillary Thyroid Cancer (PTC)." (PMID 41328346, 2026).
pneumonia (1 paper, 2023). An acute, acute and chronic, or chronic inflammation focally or diffusely affecting the lung parenchyma, caused by an infection in one or both of the lungs (by bacteria, viruses, fungi, or mycoplasma.). "Functional experiments showed that targeted silencing of ASLNC12002 could effectively inhibit EMT progression in AECIIs of patients with sepsis-induced pneumonia by restoring NR2F2/miR128-3p/Snail1 pathway." (PMID 36478088, 2023). "Here, we first found that the NR2F2 protein expression was upregulated markedly in AECIIs whether they were derived from patients with pneumonia-induced ARDS or sepsis-induced ARDS." (PMID 36478088, 2023).
pulmonary fibrosis (1 paper, 2024). Chronic progressive interstitial lung disorder characterized by the replacement of the lung tissue by connective tissue, leading to progressive dyspnea, respiratory failure, or right heart failure. "Together, these results suggested that Nr2f2 overexpression alleviated bleomycin-induced pulmonary fibrosis." (PMID 38566093, 2024). "Together, these data indicated that NR2F2 was downregulated in fibrotic lung tissues and senescent epithelial cells, suggesting its potential involvement in cellular senescence of pulmonary fibrosis." (PMID 38566093, 2024). "Consistently, histological analysis using H&E and Masson’s trichrome staining demonstrated that overexpression of Nr2f2 significantly improved the extent of pulmonary fibrosis in mice following bleomycin instillation." (PMID 38566093, 2024). "This study provides strong evidence for the potential of NR2F2 as a promising target for treating pulmonary fibrosis." (PMID 38566093, 2024). "Adenovirus-mediated Nr2f2 overexpression attenuated bleomycin-induced lung fibrosis and cell senescence in mice." (PMID 38566093, 2024). "In our study, we found that the expression of NR2F2 was significantly downregulated in the bleomycin-induced lung fibrosis mouse model and the lung epithelial cell senescence model." (PMID 38566093, 2024). "Overexpression of Nr2f2 alleviated bleomycin-induced pulmonary fibrosis." (PMID 38566093, 2024). "Importantly, we found that overexpression of Nr2f2 also alleviated bleomycin-induced experimental pulmonary fibrosis in mice." (PMID 38566093, 2024). "This indicated that NR2F2 could regulate lung epithelial cell senescence and thus participate in the development of lung fibrosis." (PMID 38566093, 2024). "However, the functional impact of NR2F2 on cellular senescence and pulmonary fibrosis, as well as the underlying mechanisms, are still not fully understood." (PMID 38566093, 2024). "Therefore, we further evaluated whether NR2F2 has a regulatory role in cell senescence during bleomycin-induced pulmonary fibrosis in mice." (PMID 38566093, 2024).
Renal cyst (1 paper, 2024). A fluid filled sac in the kidney. "Both NR2F1 and NR2F2 have been annotated with only six safety alerts, including visual impairment, renal cysts, and a bicuspid aortic valve." (PMID 39065726, 2024).
rheumatoid arthritis (1 paper, 2022). A chronic, systemic autoimmune disorder characterized by inflammation in the synovial membranes and articular surfaces. "Hence, NR2F2 may have implications for rheumatoid arthritis therapy." (PMID 36011369, 2022).